RNU4-52P (RNA, U4 small nuclear 52, pseudogene)
Gene: Small nuclear RNA gene on chromosome X (49,082,028 to 49,082,165, forward strand). Ensembl gene ENSG00000206936.
Homologues: Orthologues: chimpanzee U4 (99% identical), macaque U4 (84% identical), mouse Gm23429 (72% identical). Paralogues in human: RNU4-46P (79% identical), RNU4-51P (77% identical), RNU4-66P (76% identical), RNU4-10P (75% identical), RNU4-49P (75% identical), RNU4-43P (73% identical), RNU4-17P (70% identical), RNU4-32P (70% identical), RNU4-81P (67% identical), RNU4-24P (67% identical), RNU4-50P (67% identical), RNU4-36P (66% identical), and 81 more.